CXCR4 (C-X-C motif chemokine receptor 4)
Diseases named in the same sentence as CXCR4 in open-access papers (continued):
Sharing a sentence is not in itself a finding about the gene and the disease.
Ewing sarcoma (continued). "Integration of CXCR4-targeting strategies into first- and/or second-line treatment regimens may represent a promising treatment option for Ewing sarcoma." (PMID 23249693, 2012). "A subset of Ewing's sarcoma tumors and cell lines predominately express CXCR4." (PMID 21234386, 2011). "High expression of CXCR4 correlates with metastatic Ewing's sarcoma and with poor patient survival." (PMID 21234386, 2011). "However, given our current findings, it will be important to consider that use of EZH2 inhibitors as anti-cancer agents in Ewing sarcoma could have the on-target, but undesirable, effect of activating CXCR4." (PMID 27528222, 2016). "Indeed, a prior study showed that CXCL12 promotes the proliferation of CXCR4 positive Ewing sarcoma cells in vitro and the same study also identified a positive correlation between tumor volume and the presence of CXCR4 positive tumor cells in primary human tumors." (PMID 27528222, 2016). "Thus, in ambient, unstressed conditions, the CXCR4 promoter of Ewing sarcoma cells resides in a bivalent state and, as such, may be poised and ready for activation in response to microenvironmental cues." (PMID 27528222, 2016). "A recent example of this is the reported feedback interaction between CXCR4 and PDGF signaling in Ewing sarcoma, where high expression of CXCR4 correlates with metastasis and poor patient survival [101, 102•]." (PMID 31418125, 2019). "In this manuscript we began to address these questions and our data as yet support feedback survival signaling between the CXCR4 chemokine receptor and the growth factor and RTK network, in Ewing sarcoma PDGFRB in particular, as a plausible mechanism." (PMID 29776413, 2018). "We have very recently demonstrated that IGF2BP3 controls the expression of the chemokine receptor CXCR4 through post-transcriptional regulation of its functional partner CD164, thus promoting the motility of Ewing sarcoma cells toward the CXCR4-ligand CXCL12 under hypoxia conditions." (PMID 33673232, 2021). "CXCR4 inhibition with plerixafor (AMD3100) did not affect spheroid formation in Ewing’s sarcoma cells under 24 h simulated microgravity." (PMID 31810195, 2019). "In contrast, our previous study of CXCR4 protein expression in Ewing sarcomas revealed a correlation with tumor volume and suggested a role for CXCR4 in proliferation and tumor growth rather than metastasis." (PMID 29776413, 2018). "When CXCR4 negative Ewing sarcoma cells are deprived of growth factors they upregulate CXCR4 transcript expression and we observed that this is associated with loss of the repressive H3K27me3 modification and retention of the activating H3K4m3 modification." (PMID 27528222, 2016). "Our studies showed that Ewing sarcoma cells convert between CXCR4 negative and CXCR4 positive states in vivo and that positive cells are most abundant adjacent to areas of necrosis." (PMID 27528222, 2016). "The results of the xenograft studies confirmed that CXCR4 expression is highly plastic in Ewing sarcoma cells in vivo and that transition of cells from CXCR4 negative to CXCR4 positive states is most prominently observed adjacent to areas of necrosis." (PMID 27528222, 2016). "However, we previously noted that two Ewing sarcoma cell lines, CHLA-25 and TC-32, exist in an equilibrium state wherein 30-40% of cells express high levels of CXCR4 transcript and protein." (PMID 27528222, 2016). "Consistent with a poised, bivalent chromatin state, most Ewing sarcoma cells do not express high levels of CXCR4." (PMID 27528222, 2016). "Within our series of therapy-naive and metastatic Ewing sarcoma, however, no nuclear accumulation of CXCR4 has been observed." (PMID 23249693, 2012). "However, neither isoform correlated with CXCR4 surface expression, as in addition to HL-60, four Ewing sarcoma cell lines (A673, TC-71, VH-64, DC-ES-6) showed minimal detectable surface expression." (PMID 29776413, 2018).
Ewing sarcoma (continued). "Expression of CXCR4 increased in all Ewing sarcoma cell lines following exposure to GSK-126 and this was accompanied by loss of the H3K27me3 modification but no change in H3K4me3 enrichment at the CXCR4 promoter." (PMID 27528222, 2016). "Finally, it is clear from the current work, and from our prior studies, that not all Ewing sarcoma cells uniformly upregulate CXCR4 in response to stress." (PMID 27528222, 2016). "Due to limited sample size, multivariate analysis to assess CXCR4 expression as independent prognostic factor in Ewing sarcoma could not be performed." (PMID 23249693, 2012).
cardiac hypertrophy (18 papers, 2012 to 2025). "These are involved in cell development, differentiation, and proliferation, as are the networks with the most targets: RhoGDI, Rho Family GTPases, cAMP-mediated signaling, CXCR4 signaling, cardiac hypertrophy, and fibrosis." (PMID 40725010, 2025). "CXCL12_CXCR4 was highly expressed in each stage of cardiac hypertrophy, indicating that endothelial cells played a crucial role in regulate immune cell chemotaxis even at the baseline stage." (PMID 36805782, 2023). "These authors found similarities with the findings described in this work, such as overactivation of chemokine signaling (CXCR4), actin cytoskeleton, and cardiac hypertrophy signaling pathways." (PMID 36380187, 2022). "Our Tie2-Cre driven, endothelial CXCR4 knockout mice show hemodynamically stable aortic valve stenosis, with calcification and ventricular hypertrophy." (PMID 36148060, 2022). "EC CXCR4 KO mice also developed cardiac hypertrophy as evidenced by increased diastolic and systolic left ventricle posterior wall thickness (LVPW), cardiac myocyte size, and heart weight (HW) to body weight (BW) ratio." (PMID 36148060, 2022). "Eight pathways were common between muscle and fat: acute phase signaling, senescence pathway, cardiac hypertrophy, IL-8 signaling, CXCR4 signaling, HMGB1 signaling, GP6 signaling and PDGF signaling." (PMID 33923976, 2021). "Recently, it was reported that CXCR4 expression prevented cardiac hypertrophy induced by isoproterenol: CXCR4-KO and WT mice were subjected to chronic administration of isoproterenol for 3 weeks; biochemical as well as echocardiographic and hemodynamic measurements were performed." (PMID 27242392, 2016). "In this model, isoproterenol-induced cardiac hypertrophy was related to worsening of cardiac function, increased fibrosis, and apoptosis, implicating CXCL12/CXCR4 signaling in the regulation of cardiac hypertrophy, tissue remodeling, and apoptosis." (PMID 34072818, 2021). "KEGG pathway enrichment analysis showed that the CXCR4 and HTR2B were enriched in calcium signaling pathway, which had been extensively characterized in the role in cardiac hypertrophy and remodeling processes." (PMID 32682418, 2020). "Foxm1 deletion did not alter mRNA expression of genes critical for cardiac hypertrophy and fibrosis such as α-SMA, collagen 1α1, CaMKIIδ, TNFα, BMP4, MMP9, CXCR4 and Hey2." (PMID 23144938, 2012).
lung injury (18 papers, 2013 to 2025). "Treg may also promote fibrogenesis through TGF-β, IL-1 by inhibiting the recruitment of fibrocytes via the CXCL12/CXCR4 axis in a mouse model of acute lung injury." (PMID 36403186, 2023). "Our studies and those of our peers have shown that CXCL12 expression is markedly increased in the DRG after neuropathic pain induced by nerve injury or a chemotherapeutic agent and that inhibiting CXCR4, a CXCL12 receptor, attenuates these abnormal pain behaviours." (PMID 33658516, 2021). "Furthermore, to improve the effective mobilization of MSCs at tissue injury sites, CXCR4 overexpression in MSCs was performed and facilitated the treatment of acute lung injury in rats." (PMID 32883356, 2020). "The expression of CXCR4+ in EPCs at 7 days after TBI reflects the short-term prognosis of brain injury, and could be a potential biological marker for prognosis prediction of mild TBI." (PMID 28203485, 2017). "The functional expression of CXCR4 has been suggested to be required for the migration of MSCs to SDF-1, and then the activation of the SDF-1/CXCR4 axis could enhance the migration of MSCs following bleomycin-induced lung injury." (PMID 23834470, 2013). "After kidney injury, VCAM-1, GFP, SDF -1/CXCR4, and CD44 are upregulated in the injured tissue, which may play important roles in the migration of MSCs to the damaged area." (PMID 33424979, 2020). "Upon coupling with CXCR4, CXCL12 has been shown to lead to rapid and sustained mechanical allodynia and thermal hypersensitivity through inflammatory cytokine up-regulation in the spinal cord after nerve injury." (PMID 27760212, 2016).
ovarian tumor (18 papers, 2007 to 2025). "CXCR4 is expressed in various different tumor types and has been considered the most widely expressed chemokine receptor in many cancers including ovarian tumors." (PMID 35397601, 2022). "The mRNA expression levels of CXCR3 and CXCR4 in ovarian tumor tissues were significantly higher than those in normal ovarian tissues." (PMID 33829065, 2021). "When cultured as 3D spheroids, HeyA8 ovarian tumor cells showed a dramatic increase in surface CXCR4 protein levels as well as mRNA transcripts." (PMID 25514788, 2014). "The relationship between CXCL12 and CXCR4 expression within ovarian tumours and standard clinicopathological variables was measured using the Pearson's χ2-test." (PMID 22415233, 2012). "The expression level of CXCR4 in ovarian tumor tissues was significantly higher than that of CXCR3." (PMID 33829065, 2021). "We further addressed whether the SDF1α/CXCR4 axis is involved in CD164-induced ovarian tumor growth." (PMID 24094005, 2013). "Consequently, their findings suggest that miR-9 may exert inhibitory effects on ERK1/2 and MMP-9 expression by targeting the SDF-1/CXCR4 pathway, thereby impeding the development and progression of ovarian tumors." (PMID 39281319, 2024). "Using a metastatic ovarian tumor model in syngeneic mice, we explored whether therapy with a CXCR4 antagonist-armed oncolytic vaccinia virus activates endogenous CD103+ dendritic cell responses associated with the induction of adaptive immunity against viral and tumor antigens." (PMID 31384667, 2019). "The pre-spreading of ovarian tumors shows the expression of CXCL1 and other CXCR2 ligands as well as the expression of CXCR4." (PMID 37108425, 2023). "The post-spreading of ovarian tumors shows high expression of CCL20/liver and activation-regulated chemokine (LARC), CXCL17, and CXCR4." (PMID 37108425, 2023). "Some markers, such as CD133+, CXCR4+ or ALDH1 + CD133+, also define different CSC populations in ovarian tumors." (PMID 31159852, 2019). "Using tissue microarray technology (TMA) we analysed a large cohort of ovarian tumour samples from 289 patients for CXCL12 and CXCR4 expression." (PMID 22415233, 2012). "Baicalin acid also decreased the protein level of CXCR4 and could be activated through SDF-1a in primary ovarian tumors and ovarian neoplasms." (PMID 38094052, 2023). "Expression of CXCR4 by ovarian tumours was not shown to be independent of macroscopic residual disease, adjuvant therapy and FIGO stage (P=0.364)." (PMID 22415233, 2012). "Therefore, we analysed HER2/neu, CXCR4, and SDF-1 in 148 ovarian tumour samples by means of immunohistochemistry on tissue microarrays." (PMID 17245339, 2007).
periodontitis (18 papers, 2016 to 2025). An acute or chronic inflammatory process that affects the tissues that surround and support the teeth. "In this context, we constructed an engineered CXCR4-overexpressing exosome loaded with miR-126, which efficiently delivered its cargo to macrophages, relieving periodontitis and alleviating alveolar bone loss." (PMID 36991451, 2023). "In periodontitis, CXCR4 regulates the migration and activation of inflammatory cells in periodontal tissues, influencing disease progression and the extent of tissue damage." (PMID 40002889, 2025). "The intersection of these three machine learning approaches revealed six potential biomarkers associated with PANoptosis in periodontitis: PECAM1, CXCR4, SELP, IL2RG, CD48, and ZBP1." (PMID 40612110, 2025). "In vivo local injection of CXCR4-miR126-Exo into sites of periodontitis in rats effectively reduced bone resorption and osteoclastogenesis and inhibited the progression of periodontitis." (PMID 36991451, 2023). "Together, these findings demonstrated the promising application of engineered CXCR4-miR126-Exo to regulate M1 macrophages in periodontitis." (PMID 36991451, 2023). "In vivo local injection of CXCR4-miR126-Exo at the site of periodontitis in rats effectively reduced bone resorption and osteoclast formation and inhibited the progression of periodontitis." (PMID 38129853, 2023). "In this study, CXCR4 was found to be one of the most highly overexpressed key OS-genes in periodontitis tissues." (PMID 36148415, 2022). "For instance, CXCL12 (the chemokine stromal-cell derived factor-1) was increased in human periodontitis by targeting CXCR4." (PMID 34635105, 2021). "In chronic inflammatory conditions, SDF-1α and CXCR4 expression was observed in suprabasal layers of the epithelium of periodontitis patients." (PMID 27449062, 2016). "Immunohistochemistry was performed to analyze the expression and subcellular localization of SDF-1α and CXCR4, together with NF-kβ phosphorylation, in specimens from patients with periodontitis and in an experimental rat periodontitis model." (PMID 27449062, 2016). "Furthermore, they discovered that fibroblasts regulate NETs formation during periodontitis through the macrophage migration inhibitory factor (MIF)-CD74/CXCR4 axis." (PMID 40486514, 2025). "By generating high‐resolution three‐dimensional structures for CD27, CXCR4, and other hub proteins, AlphaFold enables the identification of key ligand‐binding interfaces—such as the CD27–CD70 interaction site—underlying immune signaling in periodontitis." (PMID 41143004, 2025). "Furthermore, our analysis of cell communication between endothelial and immune cells in individuals with smoking-related periodontitis conditions reveals that endothelial cell-derived CXCL12 influences macrophages by binding to CXCR4." (PMID 40750693, 2025). "SDF-1α and CXCR4 mRNA and protein expression levels were high in all patients with periodontitis." (PMID 27449062, 2016). "Moreover, previous study also suggested that CXCR4 can inhibit nitric oxide release from infiltrating macrophages and is involved in modulation of the mechanical sensitivity in the periodontal tissue in periodontitis." (PMID 36148415, 2022). "Therefore, we can reasonably speculate that the chemotactic activity may account for the effects of CXCR4 in the pathogenesis of periodontitis." (PMID 36148415, 2022). "Apart from IL1B and CXCR4, various other immune-related cytokines play significant roles in the onset and development of IBD and periodontitis." (PMID 40002889, 2025). "CXCR4 is significant in cell migration and immune responses, especially within the inflammatory environments of IBD and chronic periodontitis." (PMID 40002889, 2025). "IL1B and CXCR4 are key regulators of inflammation and immune responses, garnering widespread attention for their roles in diseases like IBD and chronic periodontitis in recent years." (PMID 40002889, 2025).
periodontitis (continued). "In this study, seven genes (CD19, CXCR4, FABP4, FOS, IGHD, IL2RG, and PPBP) were significantly up-regulated in periodontitis samples." (PMID 39917706, 2024). "A total of 7 genes (CD19, CXCR4, FABP4, FOS, IGHD, IL2RG, and PPBP) were upregulated in periodontitis samples." (PMID 39917706, 2024). "Therefore, by using this chemokine pair, CXCR4-Exo is hypothesized to improve the delivery efficiency of small functional molecules that will target macrophages involved in biofilm-related diseases such as periodontitis." (PMID 36991451, 2023). "Six of them were identified as key OS-genes (CXCR4, SELL, FCGR3B, FCGR2B, PECAM1, and ITGAL) in periodontitis." (PMID 36148415, 2022). "In the present study, by performing multiple bioinformatics analysis methods, we firstly identified six key OS-genes (CXCR4, SELL, FCGR3B, FCGR2B, PECAM1, and ITGAL) in periodontitis, whose expression levels were significantly upregulated." (PMID 36148415, 2022). "By employing the P. gingivalis-induced experimental rat periodontitis model, we provide evidence that SDF-1α and CXCR4 proteins play an inflammation-promoting role in the development of periodontitis by regulating the function of NF-kβ." (PMID 27449062, 2016). "In the P. gingivalis-induced rat experimental periodontitis model, SDF-1α and CXCR4 immunoreactivity was higher in gingival and periodontal ligament tissues compared to the control." (PMID 27449062, 2016).